IL1B (interleukin 1 beta)
Diseases named in the same sentence as IL1B in open-access papers (continued):
Sharing a sentence is not in itself a finding about the gene and the disease.
breast cancer (continued). "In this inquiry, the protein expression of c‐Caspase‐1 in breast cancer cells under DOX treatment was lightly reduced within 24 hours, while the expression patterns of GSDMD‐F, GSDMD‐C IL‐1β and NLRP3 hardly changed." (PMID 34369076, 2021). "In mammary tumors, CCL2 induces crosstalk between IL-1β-producing TAMs and γδ T cells, eventually results in immunosuppressive neutrophil entrainment to form a pre-metastatic niche." (PMID 34386431, 2021). "In the current study, we gathered evidence regarding the effect of IL-1β on VM in MCF-7 and MDA-MB-231 breast cancer cells, by analyzing cord formations on Matrigel and evaluating the expression of VM biomarkers." (PMID 34055597, 2021). "added DHA to breast cancer cells MDA-MB-231 and found that the activity of caspase-1 and GSDMD were enhanced, the secretion of IL-1β was increased, and showed pore-formation activity, which suggesting the occurrence of pyroptosis." (PMID 34381721, 2021). "The expression of the inflammasome components, such as IL1B, IL18, NLRP3, PYCARD, and CASP1, is significantly up-regulated in most types of breast cancer compared to that in normal tissues." (PMID 33686176, 2021). "After co-culture with IL-1β-stimulated hUCMSCs, the effects of the secreted soluble TRAIL-mediated apoptosis in breast cancer cells was investigated." (PMID 34282169, 2021). "In this study, breast cancer cells (MCF-7 and MDA-MB-231) were used to study the effect of IL-1β on the changes that can promote VM." (PMID 34055597, 2021). "In another breast cancer study, levels of IL-7, IL-8, IL-13, macrophage migration inhibitory factor (MIF), and TNF-β were increased, whereas those of CTACK, G-CSF, HGF, IL-1β, and TNF-α were decreased after IORT exposure." (PMID 34641806, 2021). "These western blot results showed that IL-1β enhanced the activation of the p38/MAPK and PI3K/Akt in breast cancer cells, and the addition of the inhibitors detained the stimulation." (PMID 34055597, 2021). "During brain metastasis of breast cancer, cancer cells can secrete IL-1β to increase JAG1 expression in astrocytes and thus promote breast cancer stem cell renewal though the Notch signaling pathway." (PMID 34034721, 2021). "A recent review described the mechanisms whereby chronic adipose tissue inflammation, with altered levels of adipokines and upregulation of cytokines (IL-1β, IL-6, and TNF-α), plays an important role in breast cancer prognosis." (PMID 34406210, 2021). "Higher expression of VE-cadherin and VEGFR-1 was observed in IL-1β treated MCF-7 and MDA-MB-231 breast cancer cells." (PMID 34055597, 2021). "The effect of IL-1β, SB203580, and GDC-0941 on VM biomarkers provided significant evidence that they are involved in the initiation of microtransformation in breast cancer cells." (PMID 34055597, 2021). "In order to address the role of tumour-derived IL-1B signalling in an immune-competent syngeneic model, we orthotopically injected IL1R1-overexpressing E0771 mouse mammary tumour cells in IL1R1fl/fl and IL1R1−/− mice." (PMID 34290237, 2021). "IL-1β induces EMT, invasion, and chemotherapeutic drug resistance in a breast cancer cell model through activation of cIAP2, c-Myc, CCDN1, MMP2, and Snail1 genes." (PMID 34220337, 2021). "According to previous studies, CITED2 regulates the expression of several growth factors such as transforming growth factor-beta (TGFβ), interleukin 11 (IL-11), interleukin 1 beta (IL-1β) and HIF-1α to promote breast cancer progression." (PMID 34569432, 2021). "Pro-inflammatory cytokines (IL-1β, IL-6, and TNF-α) not only play a potential role in the initiation of breast cancer (Section 3.2.1), but also in the progression of breast cancer." (PMID 34944905, 2021). "For example, after blocking IL-1β, CD8+ lymphocytes in breast cancer tissue were activated, leading to tumor growth restriction." (PMID 34805183, 2021).
breast cancer (continued). "Previously, IL-1β-mediated induction of IL-6 has been shown in numerous cell types, including MCF7 human breast carcinoma cells, human mast cells, fibroblasts, endothelial cells, keratinocytes, and peripheral blood monocytes." (PMID 34831450, 2021). "In previous work, we have shown that breast cancer MCF-7 cells, selected by their response to inflammatory IL-1β cytokine, acquire a malignant phenotype (6D cells) through an epithelial–mesenchymal transition (EMT)." (PMID 32244518, 2020). "Similar to this result, many investigators report that p38 MAPK plays the essential role in the IL-1β-stimulated COX-2 expression in human lung fibroblasts and MDA-MB-231 breast cancer cells." (PMID 32303181, 2020). "Studies from the same group showed that, similarly to pancreatic cancer, IL-1β, which was released by myeloid DCs under the influence of tumor-derived factors (i.e., alarmins), was key for TSLP secretion by breast cancer cells." (PMID 33042121, 2020). "In 4T1 breast cancer model, ILC3 was a major producer of IL-22, which was increased by giving IL-1β and IL-23." (PMID 32649314, 2020). "Adipocytokines such as TNF-α, IL-1β, FGF-2, and CCL2 have also been found to be involved in the regulation of LOX expression in breast cancer." (PMID 33123472, 2020). "For example, breast cancer cells are shown to respond to higher circulating levels of certain pro-inflammatory cytokines, such as TNF-α, IL-1β, and IL-6 by increasing the expression of P450 aromatase." (PMID 32731638, 2020). "Adipocytokines such as TNF-α, IL-1β, FGF-2, and CCL2, have been found to increase LOX expression in breast cancer." (PMID 33123472, 2020). "When macrophages have consumed dying mammary tumor cells by phagocytosis, AIM2 senses tumor DNA, enabling caspase-1 activation and IL-1β production." (PMID 33261061, 2020). "In breast cancer, fibroblasts sense DAMPs and activate the NLRP3 inflammasome, resulting in proinflammatory signaling upregulation and IL‐1β secretion." (PMID 32508035, 2020). "Intriguingly, GPER was also shown to trigger the activation of the IL-1β/IL1R1 transduction signaling, which in turn promoted inflammatory responses and aggressive features of breast cancer cells." (PMID 32778144, 2020). "Thus, a possible mechanism might be IL-1β and IL-23 promoting breast cancer progression via IL-22." (PMID 32649314, 2020). "Macrophage-derived IL-1β induces ROS-dependent COX2 production and activity in breast cancer cells, leading to PGE2 release in vitro." (PMID 32733461, 2020). "Human breast cancer MDA‐MB‐231 is an extremely aggressive metastatic cell line producing vast amounts of growth factors, among which IL1β was identified as a potent stimulator of NF‐κB." (PMID 31605433, 2020). "In all breast cancer cell lines tested, OSM specifically induced STAT3 phosphorylation (pSTAT3), while IL-1β induced phosphorylation of p65 (pp65), a subunit of the transcription factor NFκB." (PMID 31007849, 2019). "Another study showed that IL-1β induced the EMT process and promoted the malignancy of breast cancer cells by activating the IL-1β/IL-1R1/β-catenin pathway." (PMID 31492049, 2019). "Here, we establish that bone marrow-derived IL1β stimulates breast cancer cell colonisation in the bone by inducing intracellular NFkB and CREB signalling in breast cancer cells, leading to autocrine Wnt signalling and CSC colony formation." (PMID 31676788, 2019). "Recombinant IL1β was added to CSC cultures in vitro, and it recapitulated the effect of CM in stimulating CSC colony formation in breast cancer cells (MCF7; p < 0.0001, MDA-MB-231_BH; p < 0.0001)." (PMID 31676788, 2019). "Inflammatory cytokines, including IL1B and TNFA, were expressed in breast cancer tissues but only at very low levels in breast cancer cell lines." (PMID 31533776, 2019). "In summary, CCL2 has the potential to drive via IL-1β the γδ T cell/IL17/neutrophil axis, which promotes breast cancer metastasis." (PMID 31921102, 2019).
breast cancer (continued). "We also demonstrate that co-treatment of ER− breast cancer cells with both OSM and IL-1β leads to a synergistic increase in IL-6 secretion." (PMID 31007849, 2019). "In breast cancer cells, epithelial-to-mesenchymal (EMT) and stem-cell-like phenotypes were attenuated by either anti-IL-6 or anti-IL-1β antibody treatment." (PMID 31231372, 2019). "IL-1β increases the expression of osteoprotegerin (OPG, a promoter of invasion and metastasis of breast cancer) and induces its secretion by activating the p38 mitogen-activated protein kinase (MAPK) signaling pathway." (PMID 31500658, 2019). "In particular, interleukin-1β (IL-1β) and tumor necrosis factor-α (TNF-α) proinflammatory cytokines have an important role in the interaction between breast cancer cells and their microenvironment." (PMID 31093512, 2019). "In patients with breast cancer, a positive correlation of CCL2 with IL-1β and with macrophage marker CD68 in all breast cancer types was shown." (PMID 31921102, 2019). "A link between IL-1B and OPG has been recently found in breast cancer primary tumour development and metastasis and will be discussed later in this review." (PMID 29760166, 2018). "Taken together, these data suggest a role of IL-1B and OPG in mediating breast cancer metastasis and inflammation." (PMID 29760166, 2018). "T cell-derived cytokines, including IL-1β, TNF-α and IFN-γ, enhanced significantly TGF-β1-induced EMT in breast cancer (FMC-7) and lung cancer (A549) cell lines." (PMID 29432497, 2018). "A positive correlation between IL-1B expression, OPG and CCL2 has been found in human breast cancer genome-wide mRNA expression array." (PMID 29760166, 2018). "Studies in breast cancer cells clearly demonstrate that Jagged1, ICN1, and ICN3 are required for IL-1β transcriptional activation occurring at the RBP-Jk DNA binding site at −2,085 from the translation start site." (PMID 30154786, 2018). "Conversely, lung cancer, melanoma, breast cancer and HNSCC, demonstrated that NLRP3 inflammasomes, IL-1β and IL-18 promote tumor growth, proliferation, invasion and metastasis." (PMID 30447690, 2018). "Macrophages are the source of exogenous IL-1β, their co-culture with breast cancer cell lines enhances OPG expression in breast cancer cells." (PMID 28927416, 2017). "OPG, IL1B, and CCL2 mRNA in normal and breast cancer human tissue samples were determined by qPCR using a panel of commercially available cDNAs." (PMID 28143606, 2017). "For example, a yoga intervention in breast cancer survivors reported decreases in IL-6, TNF-α, and IL-1β." (PMID 28694775, 2017). "In addition, estrogen levels are positively correlated with IL-1β expression in breast tissue and that estrogen stimulates IL-1β production in breast cancer xenografts, raising a possibility that the inflammasome activation could be involved in estrogen-induced tumor growth." (PMID 29312618, 2017). "Breast cancer cells were treated with both p38 (SB202190) and p42/44 (U0126) MAPK inhibitors simultaneously with IL1B for 24 h." (PMID 28143606, 2017). "Breast cancer cells were simultaneously treated with MAPK inhibitors (10 μM) and IL1B (10 ng/mL) for 24 h." (PMID 28143606, 2017). "We observed that the p38 and p42/44 inhibitors repressed the IL1B-mediated induction of OPG mRNA and secreted OPG protein in all three breast cancer cell lines tested." (PMID 28143606, 2017). "We observed statistically significant higher mRNA expression levels (lower delta Ct values) for CCL2, IL1B and OPG in the stage I breast cancer samples relative to normal samples." (PMID 28143606, 2017). "Characteristics of breast cancer controls (n = 885) across levels of several inflammation markers (ox-LDL, TNF-α, and IL-1β) in the Malmö Diet and Cancer cohort." (PMID 27391324, 2016). "Our findings indicate that luminal-type breast cancer cells acquire the ability to produce IL-6 through cancer cell TG2 overexpression and IL-1β from the tumor microenvironment." (PMID 27609180, 2016).
breast cancer (continued). "Considering that E2 and G-1 trigger the expression of IL1β in CAFs and IL1R1 in breast cancer cells, we then assessed that conditioned medium from CAFs exposed to E2 and G-1 does induce PTGES protein expression in SkBr3 and MCF-7 cells exposed to E2 or G-1." (PMID 27072893, 2016). "Here, we demonstrate that signalling mediated by the G protein estrogen receptor (GPER) triggers IL1β and IL1R1 expression in CAFs and breast cancer cells, respectively." (PMID 27072893, 2016). "In spite of many attempts where the role of either IL-1β or HIF-1α was evaluated, detailed mechanisms for their effects on breast cancer cell migration under hypoxia are still unclear." (PMID 26696754, 2015). "In summary, an interaction between CD40 on MDA-MB231 breast cancer cells and CD40L on activated T cells increases the production of Th17 differentiating cytokines including TGF-β, IL-1β, IL-6, and IL-21." (PMID 25992978, 2015). "Of note, although TNF-α and IL-1β increased the proteoglycan degradation, autophagy was induced by TNF-α and IL-1β in chondrocytes, AF cells, fibrosarcoma L929 cells and breast cancer cells." (PMID 26165348, 2015). "On the other hand, the secretion of IL-6, IL-1β and TNF was significantly lower in breast cancer patients." (PMID 25992611, 2015). "IL-1β, a potent activator of NF-κB signaling, produced an upregulation in chemokines CCL-2, -7, -8 similar to that seen by co-culture with breast cancer cells." (PMID 24068959, 2013). "We recently reported that in Th1 cytokine enriched microenvironment, MIG/CXCL9 and IP-10/CXCL10 were upregulated while IL-1β and IL-6 were downregulated with concomitant reduction in the percentage of MDSC in a 3D breast cancer model." (PMID 23394575, 2013). "Cytokines produced by cancer tissue and the expression of interleukin (IL)-1β, IL-6, IL-8, IL-10, IL-12, and IL-19, monocyte-chemoattractant-protein (MCP-) 1, and macrophage-inflammatory-protein- (MIP-) 1β are upregulated in breast cancer." (PMID 23710200, 2013). "Breast cancer MCF-7 cells have a poor invasive phenotype, although, under IL-1β stimulus, acquire invasive features." (PMID 22655200, 2012). "Recently, much attention has been given to the roles of inflammatory chemokines and cytokines in breast cancer, with emphasis on the chemokines CCL2 and CCL5, and the cytokines tumor necrosis factor α (TNFα) and interleukin 1β (IL-1β)." (PMID 21486440, 2011). "Interestingly, in the 4T1 immunocompetent model of breast cancer, changes in intra-tumoral IL-1β levels correlate negatively with changes in MDSC infiltration after three weeks of therapy, where increases in IL-1β following treatment with mcr84 were associated with reduced MDSC infiltration." (PMID 19888452, 2009). "In addition, the level of SP1 in TDEs increases, which favors the secretion of IL‐1β by neutrophils through the activation of the TLR4‐NFκβ pathway, ultimately aggravating lung metastasis of breast cancer." (PMID 39630109, 2025). "Recent studies reveal that breast cancer-derived cathepsin C (CTSC) activates neutrophil membrane protease 3 (PR3), triggering Interleukin-1β (IL-1β)/nuclear factor-kB (NF-κB) signaling cascades through pro-IL-1β cleavage." (PMID 40568594, 2025). "A similar mechanism can be induced in breast cancer cells upon the activation of EGFR by amphiregulin, whereas autocrine and paracrine stimulation of IL-1R by IL-1β secreted by several types of tumor cells can lead to the constitutive activation of the NF-κB pathway." (PMID 39858071, 2025). "This not only strengthens neutrophil self‐recruitment via the CXCL2 autocrine but also promotes neutrophil secretion of IL‐1β through the TLR4‐NFκβ pathway, thereby remodeling the lung microenvironment and contributing to the promotion of lung metastasis of breast cancer." (PMID 39630109, 2025).
breast cancer (continued). "Further, IL-1β has been reported to play a pivotal role in the growth of primary tumors and in the promotion of epithelial-to-mesenchymal transition (EMT), leading to migration and invasion in breast cancer." (PMID 40725140, 2025). "Moreover, TGF-β was shown to upregulate L1CAM to trigger binding of integrins, resulting in induction of IL-1β secretion and EMT promotion in pancreatic and breast cancers." (PMID 38263290, 2024). "Since GSDMD is associated with better prognosis in this tumor type, these results suggest that in breast cancer, GSDMD may have other functions besides mediating the release of IL-1β." (PMID 39224600, 2024). "Despite the clinical signs, which resemble the presence of acute inflammation, IBCs produce inflammatory cytokines (such as IFNG, TNF, IL1A, IL1B, and IL8) at similar levels to other breast cancer subtypes, while the host inflammatory cell infiltration is low in the IBC stroma." (PMID 39103878, 2024). "In addition, adding exogenous IL-1B also facilitated infiltration and invasion of ER + ve, ER + ve, HER2 + ve human BT-474 breast cancer cells and increased stem-cell-like phenotypes, invasion of ER + ve MCF7 cells." (PMID 38800348, 2024). "IL-1β and IL-6 can induce EMT in breast cancer cells via the STAT3 pathway and promote angiogenesis, which suggests that BMAs may similarly exacerbate bone destruction in lung cancer bone metastasis." (PMID 38571500, 2024). "Among these different CAF subtypes, iCAFs are reported to have a particular effect on chemoresistance in breast cancer patients, probably due to their high secretion of cytokines involved in therapy resistance, such as CXCL1–3, CCL2, CSF3, CXCL10, IL1β and LIF." (PMID 36710348, 2023). "Furthermore, IL‐1β, TNF‐α, and IL‐4 did mediate the relationship between psychological distress and cognitive function in breast cancer survivors." (PMID 36965094, 2023). "On the other hand, targeting IL-1β could also promote TAM polarization toward the M2 phenotype, which results in breast cancer metastasis." (PMID 36823153, 2023). "To confirm that the antitumor immunity in the 4T1 breast cancer mouse model was induced by GSDMBNT mRNA@LNP-mediated pyroptosis, we investigated the expression of ICD biomarkers (CRT and HMGB1) and pyroptosis-related cytokines (IL-1β and IL-18)." (PMID 37454146, 2023). "Peripheral blood samples were collected from 187 rural working women with breast cancer, occupationally exposed or not to pesticides, to quantify the levels of cytokines IL-1β, IL-12, IL-4, IL-17-A, and TNF -α." (PMID 37942322, 2023). "Our previous work, utilizing an in vitro model of non-invasive epithelial human breast cancer cells (MCF-7), demonstrated that treatment with the inflammatory cytokine IL-1β transforms these cells to malignancy (thereafter, 6D cells), through an epithelial–mesenchymal transition (EMT) process." (PMID 37686042, 2023). "This study demonstrated IL‐1β, TNF‐α, and IL‐4 as potential pathways to CRCI in response to ongoing psychological distress, which provided evidence for the involvement of psychological distress in CRCI in breast cancer survivors." (PMID 36965094, 2023). "For instance, cytokines like IL-1β, IL-6, IL-8, and TNF-α play a crucial role in breast cancer." (PMID 37569777, 2023). "Inhibition of cathepsin K may inhibit breast cancer bone metastasis by reducing the expressions of TNF-α, IL-6, and IL-1β." (PMID 37398678, 2023). "Likewise, CAAs cocultured with breast cancer cells have been shown to increase their expression of MMP-11 as well as proinflammatory cytokines (IL-6 and IL-1β) and thereby promote tumor cell invasion and metastasis." (PMID 36670988, 2023). "Additionally, docosahexaenoic acid (DHA) has been proven to trigger MDA-MB-231 breast cancer cell pyroptosis via the caspase-1/GSDMD pathway, inducing IL-1β secretion, translocation of HMGB1 to the cytoplasm, and pore formation in the cell membrane." (PMID 38016064, 2023).